DDX3Y (DEAD-box helicase 3 Y-linked)
Description:
Probable ATP-dependent RNA helicase. During immune response, may enhance IFNB1 expression via IRF3/IRF7 pathway (By similarity).
Synonyms: DBY
Tractability: PROTAC: UniProt records ubiquitination sites on it; ubiquitination databases record sites on it; its protein half-life has been measured.
Gene: Protein-coding gene on chromosome Y (12,904,108 to 12,920,478, forward strand). Ensembl gene ENSG00000067048.
Subcellular location: Cytoplasm; Nucleus
Subcellular location (Human Protein Atlas): Cytosol; Plasma membrane
Gene Ontology:
Molecular function: protein binding; ATP binding; ATP hydrolysis activity; nucleic acid binding; RNA helicase activity
Biological process: cell differentiation; gamete generation; negative regulation of gene expression
Cellular component: cytoplasm; cytosol; membrane; nucleus; P granule
Homologues: Orthologues: chimpanzee DDX3Y (98% identical), macaque DDX3Y (98% identical), mouse Ddx3y (89% identical), rat Ddx3y (87% identical), tropical clawed frog ddx3x (84% identical), zebrafish ddx3xb (78% identical), zebrafish ddx3xa (77% identical). Paralogues in human: DDX3X (92% identical), DDX4 (43% identical), DDX17 (33% identical), DDX5 (33% identical), DDX42 (31% identical), DDX46 (28% identical), DDX41 (28% identical), DDX23 (27% identical), DDX43 (27% identical), DDX59 (25% identical), DDX53 (25% identical), DDX21 (24% identical), and 26 more.